ALB (albumin)
Diseases named in the same sentence as ALB in open-access papers (continued):
Sharing a sentence is not in itself a finding about the gene and the disease.
breast carcinoma (continued). "OBJECTIVE: To evaluate the predictive value of the mean platelet volume–to–albumin (MPV/Alb) ratio for pathological complete response (pCR) in patients with human epidermal growth factor receptor 2 (HER2)-positive breast cancer (BC) treated with neoadjuvant chemotherapy (NACT)." (PMID 41979751, 2026). "For instance, low preoperative serum albumin has been associated with systemic inflammation and poor nutritional status, which are known negative prognostic indicators in breast cancer patients." (PMID 41226320, 2025). "Elements of systemic inflammation, such as platelets, lymphocytes and high-sensitivity C-reactive protein (hs-CRP), and biochemical markers in the blood, such as C-reactive protein levels and albumin levels, are valuable prognostic indicators for cancer, including breast cancer." (PMID 40860681, 2025). "Based on this evidence, ALB and BMI, which reflect energy reserves and protein metabolism status, support the integrated consideration of both factors in the prognostic evaluation of advanced breast cancer." (PMID 40535131, 2025). "In 2005 and 2021, the FDA approved Abraxane, paclitaxel albumin protein‐bound nanoparticles (~130 nm) for intravenous use to treat breast cancer, and Fyarro, sirolimus albumin protein‐bound nanoparticles for intravenous use to treat perivascular epithelioid cell tumor (PEComa), respectively." (PMID 41211661, 2025). "However, the relationship between the prevalence of breast cancer (BC) and the neutrophil-percentage-to-albumin ratio (NPAR), a recently identified biomarker of inflammation, is not well established." (PMID 40357031, 2025). "Albumin-bound paclitaxel is a drug approved by FDA for the treatment of advanced breast cancer." (PMID 38262996, 2024). "Therefore, the proposed association between low preoperative serum albumin levels and poor patient outcomes may be specific only to the surgical procedure and patient population studied and not conversely applicable to other types of cancer like lung, kidney, or breast carcinoma." (PMID 38707022, 2024). "The mediating effect of albumin in the association between BaP and breast cancer development has not been investigated in other studies yet." (PMID 39548533, 2024). "We prepared and characterized polystyrene NPs withdifferent coatings of poly(ethylene glycol), bovine serum albumin,chitosan, and cell membranes from a human breast cancer cell line.The coating was found to affect the colloidal stability, adhesion,and elastic modulus of NPs." (PMID 38159050, 2024). "A total of three studies investigated the value of albumin in predicting a pCR in breast cancer." (PMID 38801441, 2024). "Albumin and hemoglobin adduct of estrogen-3,4-quinone and estrogen-2,3-quinone may serve as biomarkers for early detection of breast cancer." (PMID 39664179, 2024). "In addition to inflammatory factors, nutritional indicators can also predict the prognosis of breast cancer, and pre-therapy serum albumin has been used as a predictor to assess disease progression, disease severity and prognosis." (PMID 38766483, 2024). "In contrast to breast cancer, some preoperative parameters (C-reactive protein, albumin, fibrinogen, fibrinogen/albumin, NLR, etc.)have considerable potential to be early sensitive biomarkers of IGM, providing a useful guide for differential diagnosis of two diseases." (PMID 38529282, 2024). "The combination of albumin paclitaxel and immunotherapy had performed a positive effect, suggesting that this treatment may be an effective method for heterogeneous breast cancer with metastatic carcinoma." (PMID 36862895, 2023). "It is widely acknowledged that serum albumin level independently plays a significant role in predicting survival outcomes in various types of cancers, such as lung, pancreatic, gastric, hepatocellular, and breast cancer." (PMID 37836576, 2023).
breast carcinoma (continued). "Serum albumin has been adopted to appraise disease severity, progression and been considered as an independent factor of poor prognosis in varieties of cancers including breast carcinoma." (PMID 36662756, 2023). "In addition, high expression of Cav-1 in breast cancer is indicative of breast cancer sensitivity to albumin-paclitaxel." (PMID 37828916, 2023). "However, only rapamycin-albumin nanoparticles have been evaluated in breast cancer patients among other tumor types, such as cervical, bladder, ovarian, and prostate carcinomas." (PMID 35267507, 2022). "This reduced albumin level corresponds to the poor survival of breast cancer subjects." (PMID 36558514, 2022). "In order to examine the effect that circulating proteins play in mediating the effects of muscle-derived myokines on breast cancer, perfusates were prepared either with bovine serum albumin (BSA) or dextran, with the parameters of the contraction and collection remaining identical." (PMID 36388131, 2022). "This study observed a significantly decreased albumin level in breast cancer subjects." (PMID 36558514, 2022). "Finally, the results were not significantly altered when analyzing a subsample including albumin as an additional factor in the multivariate analyses; adjusted OR for breast cancer in serum zinc Q4 versus Q1 was 1.05 (0.75–1.47)." (PMID 34224055, 2021). "We chose alanine transaminase (ALT), aspartate transaminase (AST), lactate dehydrogenase (LDH), gamma-glutamyltransferase (GGT), alkaline phosphatase (ALP), glucose (GLU), immunoglobulin A (IgA), IgG, IgM, and ALB as parameters to evaluate the nutritional status of breast cancer patients." (PMID 33859986, 2021). "Nanoparticles of Human Serum Albumin (NC) labelled with 99mTc are widely used in Nuclear Medicine and represent the gold-standard for the intraoperative detection of the sentinel lymph node in many kinds of cancer, mainly breast cancer and melanoma." (PMID 34361162, 2021). "Inflammation-based prognostic scores, including the neutrophil to lymphocyte ratio, lymphocyte to monocyte ratio, platelet to lymphocyte ratio and C-reactive protein/albumin ratio, have been analyzed to evaluate their prognostic predictive value in breast cancer, but the results are controversial." (PMID 34692474, 2021). "We envisioned that intraoperative real-time fluorescence imaging with a human serum albumin decorated indocyanine green probe could enable complete surgical removal of breast cancer in a mouse model." (PMID 33763353, 2021). "Therefore, this study aimed to assess the impact of ONS on anthropometric and biochemical parameters, including albumin and lipid concentration in patients diagnosed with breast cancer and treated by adjuvant chemotherapy." (PMID 34684550, 2021). "In case 1, a 72-year-old Japanese woman with bilateral geographic choroiditis reported for a follow-up visit with a complaint of blurred vision in both eyes for 2 months after starting nanoparticle albumin-bound paclitaxel chemotherapy for multiple metastases of her breast cancer." (PMID 34284818, 2021). "Prompted by the promising perspectives derived from combining MelaSil_Ag NPs with a biomodulator for improving cell internalization and targeting, a systematic study was undertaken to explore the potential of human serum albumin (HSA) to modify the NPs to target breast cancer cells." (PMID 32733871, 2020). "A gelatin-albumin (Gel-Alb) hybrid nanoparticle was generated and evaluated for its drug efficacy as an anti-cancer drug delivery system in a panel of subtype-specific breast cancer cell lines." (PMID 32466129, 2020). "Doxil® is the liposomal formulation of doxorubicin, approved for the management of Kaposi’s sarcoma as well as refractory breast and ovarian cancer, while Abraxane® is an albumin-based nanoparticles (NPs) of paclitaxel and approved for the management of metastatic breast cancer." (PMID 33374391, 2020).
breast carcinoma (continued). "Overall, we believe albumin–QDs nanoplatform could be a potential nano-theranostic for bioimaging and targeted breast cancer therapy." (PMID 30660179, 2019). "Albumin–QDs theranostics showed enhanced cytotoxicity and internalization into breast cancer cells that could be traced by virtue of their high fluorescence quantum yield and excellent imaging capacity." (PMID 30660179, 2019). "For example, PLGA/goserelin acetate (Zoladex) was first approved by the FDA for treating prostate and breast cancer in 1989, PEGylated liposomal doxorubicin (Doxil) was approved for various types of cancer in 1995, and an albumin/paclitaxel system (Abraxane) was approved for breast cancer in 2005." (PMID 29657772, 2018). "Hypothetically, an accumulation of SPARC in breast cancer cells and stroma could increase its ability to bind albumin, therefore might serve as a predictive marker for nab-paclitaxel." (PMID 28061451, 2017). "Serum albumin is a commonly used parameter to assess nutritional status in cancer and has been described as an independent prognosticator of survival in lung, pancreatic, gastric, colorectal, and breast cancers." (PMID 28558699, 2017). "The application of albumin-based MnO2 NPs showed clinical relevance by modulating tumor hypoxia and enhancing radiotherapy efficacy in xenograft tumor models of murine and human breast cancers." (PMID 29255705, 2017). "Reduction of albumin level is an independent predictive indicator of breast cancer." (PMID 28702147, 2017). "Nevertheless, significantly lower risks of breast cancer with increasing calcium levels were observed among postmenopausal women (e.g., HR: 0.89, 95% CI: 0.82–0.97 for the fourth compared to the first quartile of calcium when adjusted for albumin)." (PMID 27608013, 2016). "Moreover, previous studies have reported several factors related to poor outcomes of breast cancer patients, such as albumin, LDH, bilirubin and cholesterol." (PMID 26600129, 2015). "A study investigated the effect of baseline serum albumin levels on 180 breast cancer patients." (PMID 21176210, 2010). "In addition oestradiol levels were measured in relation to sex hormone binding globulin (SHBG), albumin levels, oestrogen receptor status and family history of breast cancer." (PMID 2393409, 1990). "In a clinical trial (CA201) for the first-line treatment of advanced breast cancer conducted in China, the objective response rate after albumin-paclitaxel treatment reached 56%, while the control group using conventional chemotherapy drugs could only reach 27%." (PMID 40292112, 2025). "In addition to evaluating patient’s nutritional status, serum albumin level might be an indicator that links to disease outcomes in many cancer types including breast cancer." (PMID 40416620, 2025). "Therefore, serum albumin levels can be used as a prognostic marker for breast cancer." (PMID 38072672, 2024). "In the univariate regression analysis, p-values of albumin-globulin ratio, total cholesterol, lipoprotein a, CA153, gamma-glutamyl transferase, α-HBDH, alkaline phosphatase, and creatine kinase were < 0.05, suggesting potential associations with breast cancer metastasis." (PMID 39098907, 2024). "Similarly, albumin, estradiol, and both LDL and HDL cholesterol may play a role in linking BaP exposure to breast cancer risk." (PMID 39548533, 2024). "The four-way decomposition mediation analysis showed a suggestive mediation through estradiol and PTH in the association of NO2 and PCB153 exposures with breast cancer risk, whereas albumin, estradiol, LDL and HDL cholesterol may play a role in the association between BaP and breast cancer risk." (PMID 39548533, 2024). "The lowest albumin concentration was observed in the group of patients with breast cancer in the postmenopausal period, with a slight decrease in fibroadenomas, while in the premenopausal period its highest concentration was in the group of patients with breast cancer." (PMID 39452912, 2024).
breast carcinoma (continued). "As a new generation of paclitaxel preparations, albumin-bound paclitaxel (albumin-paclitaxel) is a first-line drug for triple-negative breast cancer chemotherapy and occupies an extremely important position in the chemotherapy of breast cancer and other malignant tumors." (PMID 37828916, 2023). "In addition, cytotoxicity and cell uptake experiments showed that, after encapsulation of Nintedanib into folic acid modified albumin microspheres, the cell uptake ability of the drug was significantly enhanced, while the inhibition rate of breast cancer cell MCF-7 was higher." (PMID 35126516, 2022). "Early breast cancer patients receiving paclitaxel at 175 mg/m2 every 3 weeks, in two BMI groups (normal, 18–24.9 kg/m2 and overweight/obese, ≥25 kg/m2, respectively), matched for age, serum albumin and bilirubin levels using minimization technique, were included." (PMID 33826243, 2021). "For example, breast cancer patients with high tumor SPARC expression were seriously more sensitive to an albumin-bound paclitaxel 22, potentially because of the strong binding capacity of SPARC to albumin, which could lead to the accumulation of paclitaxel in local tumor microenvironment." (PMID 31897236, 2020). "Similarly, the alpha-specific PI3K inhibitor alpelisib showed promising activity in combination with albumin-bound paclitaxel in patients with metastatic HER2-negative breast cancer, most (30/43, 70%) of whom had received at most one prior line of chemotherapy in the metastatic setting." (PMID 33138866, 2020). "Therefore, the PTX loaded VE-Albumin core-shell nanoparticles could be a potential strategy for the treatment of MDR breast cancer." (PMID 30366367, 2018). "One of the nanomedicines that are used clinically in the treatment of cancer is nanoparticle albumin-bound paclitaxel (brand name: Abraxane), which showed less toxic and superior efficacy compared with polyethylated castor oil-based paclitaxel in the treatment of breast cancer." (PMID 27531898, 2016). "This information could guide further development of albumin-bound cytotoxics in breast cancer." (PMID 23638089, 2013). "In the present study, only 7% of patients had such comorbidity (only one patient had planned adjuvant treatment altered) and therefore this would suggest that there may be an interaction between breast cancer and albumin concentrations, which might impact on the survival of these patients." (PMID 17375036, 2007). "Therefore, the prognostic value of C-reactive protein and albumin in patients with primary operable breast cancer remains unclear." (PMID 17375036, 2007). "Furthermore, albumin in the breast cancer cell cytosol may inhibit tumour growth and tumour cell proliferation by modulating the activities of autocrine growth regulatory factors." (PMID 17375036, 2007). "Nanoparticle albumin-bound paclitaxel (NAB-PTX) has been employed to deliver trastuzumab (T-mab) and pertuzumab (P-mab) for the treatment of HER2-positive primary breast cancer (PerSeUS-BC04)." (PMID 40092984, 2025). "Using training and validation cohorts of 1583 patients with breast cancer, the relationship between the cancer prognosis and a novel systematic oxidative stress score (SOS based on LDH, TBIL, CRE, ALB, and BUN) was investigated." (PMID 39958338, 2025). "The present research is a meta-analysis aimed at quantifying the influence of the hemoglobin, albumin, lymphocyte, and platelet (HALP) score on the overall survival (OS) and disease-free survival (DFS) in breast cancer patients." (PMID 41409247, 2025). "In dogs with mammary tumors, the combined PCA of leukogram, albumin/globulin, age, and tumor size was a strong predictor of survival rate." (PMID 39852907, 2025). "The clinical and follow-up data of 200 breast cancer patients were retrospectively analyzed in this study, and the value of LANR was determined as follows: LANR, lymphocytes × albumin/neutrophils." (PMID 38766483, 2024).
breast carcinoma (continued). "Using this method, albumin was extracted and purified by the adsorption and release of serum albumin by HAP and diagnosed using SERS to detect breast cancer." (PMID 38072672, 2024). "Albumin-bound paclitaxel, approved by the US FDA for the first-line treatment of non-small cell lung cancer, breast cancer, ovarian cancer, and pancreatic cancer, has been demonstrated to simplify pre-treatments and reduce allergic events during chemotherapy." (PMID 39777344, 2024). "The study explored the impact of pretreatment serum albumin-to-alkaline phosphatase ratio (AAPR) and changes in tumor blood supply on pathological complete response (pCR) in breast cancer (BC) patients following neoadjuvant chemotherapy (NACT)." (PMID 39013971, 2024). "The antioxidant activity was measured using the H2O2 test, the anti-inflammatory activity was identified using the egg albumin assay, and the anti-cancer activity was analyzed using the MTT assay on MCF-7 breast cancer cell lines." (PMID 39449928, 2024). "Some top-ranked enrichments are straightforward to interpret, such as kidney for urine albumin-creatinine ratio, osteoblast for bone mineral density, and MCF-7 for breast cancer." (PMID 38167462, 2024). "We explored the relationship between preoperative lymphocytes, neutrophils and albumin (LANR) and progression-free survival in breast cancer patients." (PMID 38766483, 2024). "The groups with mammary neoplasms (GI and GII) showed a higher abundance of the proteins protocadherin 17 and albumin." (PMID 39057100, 2024). "On the same day, the mice were treated systemically with PFD, nanoparticle albumin‐bound paclitaxel (nab‐PTX), an FDA‐approved chemotherapy drug for breast cancer, as well as a combination of the two, respectively." (PMID 36651490, 2023). "EOC202 is a recombinant human LAG-3 fusion protein injection combined with albumin-bound paclitaxel for the treatment of patients with HR+, HER2- advanced breast cancer with progression after endocrine therapy (NCT05322720)." (PMID 35954196, 2022). "The serum albumin/globulin ratio (AGR) has been suggested as a prognostic marker for colorectal cancer, lung cancer, breast cancer, and nasopharyngeal carcinoma." (PMID 36547159, 2022). "Albumin is a major component of Abraxane®, which has been approved by the FDA to treat breast cancer." (PMID 35268583, 2022). "Abraxane®, which consists of albumin nanoparticles of around 130 nm entrapping PTX, was approved in the 2000s by the FDA and EMA for the treatment of different neoplasms, including breast cancer." (PMID 35267507, 2022). "For instance, adenoviral-mediated gene transfer of canstatin-human serum albumin fusion protein (CanHSA) was performed to evaluate the validity of treatment against tumors in mouse models, including xenografts of MDA-MB-231 breast cancer cells and PC-3 cells." (PMID 34434564, 2021). "The results showed that ALB, NMR, NLR and LMR were independent prognostic hematological factors for OS in breast cancer patients." (PMID 34069272, 2021). "After univariate and multivariate analyses, we identified five independent systematic oxidative stress indicators (TBIL, BUN, CRE, ALB, and BUN) to calculate SOS, which is an independent prognostic factor for breast cancer patients." (PMID 34659642, 2021). "These authors conjugated methotrexate (MTX) to human serum albumin (HSA) and, after the crosslinking such protein, they obtained NPs that were decorated by Tmab to treat HER2+ breast cancer." (PMID 32859026, 2020). "In addition, high levels of fibrinogen-to-albumin ratio (FAR), a novel inflammation-based biomarker, are associated with poor outcomes in various cancers, including esophageal squamous cell carcinoma (ESCC), breast cancer, gallbladder cancer, and soft tissue sarcoma." (PMID 32375697, 2020). "We optimized the delivery parameters with fluorescent-labeled bovine serum albumin, and successfully delivered fluorescent PKAs through CRISPRMAX into breast cancer cells." (PMID 33374889, 2020).